CD4 (CD4 molecule)
Diseases named in the same sentence as CD4 in open-access papers (continued):
Sharing a sentence is not in itself a finding about the gene and the disease.
syphilis (continued). "Notably, the peripheral blood of early syphilis patients exhibited a significant decrease in CD4+T cells compared to CD8+T cells, potentially attributed to the pyroptosis of CD4+T cells." (PMID 38694502, 2024). "After syphilis treatment, CD4+ T cells returned to “normal” levels." (PMID 36291681, 2022). "Some studies have shown that syphilis might increase HIV viral load and decrease CD4 cell count in PLWH, increasing risk of HIV transmission." (PMID 35587482, 2022). "Future studies should examine whether CD4/CD8 ratio modifies cellular response against syphilis and alters the degree of lymphocyte depletion." (PMID 36587188, 2022). "Higher VDRL titre during syphilis was associated with a greater decline in total lymphocyte, CD4+, and CD8 + T-cell levels in the univariable but not the multivariable analysis." (PMID 36587188, 2022). "However, the median CD4 cell counts of neurosyphilis group was 219 cells/μL, which was significantly higher than that of syphilis group (90 cells/μL), (P = .048)." (PMID 34678871, 2021). "Participants were actively engaged with health services and on ART with high CD4 cell counts and suppressed HIV VLs, which could potentially exclude those most at risk of active syphilis." (PMID 33570464, 2021). "Factors associated with the time to CD4+ T-Cell recovery following initiation of ART between HIV-infected MSM with or without syphilis screening during 2008 and 2012 in Guangzhou, China." (PMID 34307399, 2021). "Similarly, experiences with POCT for syphilis and CD4+ T-cell enumeration showed wide variability in uptake, indicating the potential for detrimental effects in some settings or sub-populations." (PMID 31917797, 2020). "On the multivariate analysis, only higher CD4 cell count nadir (but not most recent CD4 cell count), younger age and peri-incident syphilis were associated with increased risk of HCV infection." (PMID 28253838, 2017). "However, in Curitiba, this procedure is no longer being adopted because of the use of rapid tests for syphilis, and it was necessary to use venous blood samples collected for the first CD4 T lymphocyte count." (PMID 27598785, 2016). "Additionally, the implementation of an integrated package of three POC assays led to an overall increase of the coverage of all three, hemoglobin, syphilis and CD4+ cells tests, among pregnant women." (PMID 26308345, 2015). "For the HIV-infected patients with concurrent syphilis, those who had neurological symptoms when performing lumbar puncture, CD4 cell counts <350 per μL, and with serological TRUST titer ≥16 was 4.9-, 4.3-, and 4.1-fold, respectively, more likely to be diagnosed as having neurosyphilis." (PMID 26559304, 2015). "For all the HIV/syphilis co-infected patients with or without neurological symptoms, the risk factors of neurosyphilis were having neurological symptoms, CD4 <350 per μL, serological TRUST titer ≥1:16." (PMID 26559304, 2015). "Additionally, a study from Spain demonstrated that, among 118 coinfected patients, syphilis resulted in similar CD4 cell and viral load effects among one-third of patients." (PMID 26316953, 2013). "In relation with CD4+ cell levels, it was found that only 7 (36.8%) of 19 patients had less than 350 cells/mm3 and 6 (30%) had a VL higher than 4 log10 copies/mL at the time of syphilis diagnosis." (PMID 26316966, 2013). "If these women are excluded and person-time censored when an additional 3 women started on therapy after delivery, the association between non-EBF and transmission remained unchanged (RH = 3.09 95% CI 1.25–7.64 adjusted for viral load, CD4 count, syphilis status and birthweight)." (PMID 18159246, 2007). "The association between non-EBF and higher risk of post-natal HIV transmission was slightly attenuated but remained significant (RH = 2.68 95% CI: 1.28–5.62) after adjusting for maternal CD4 count, plasma viral load, syphilis screening results and low birthweight." (PMID 18159246, 2007).
syphilis (continued). "However, the impact of syphilis on CD4+ cells or HIV viremia seems marginal." (PMID 34832520, 2021). "Syphilis increases the recruitment of HIV-1 susceptible inflammatory cells, such as activated macrophages and CD4+ and CD8+ T cells, to the infection site, leading to an increase in HIV viral load, a decrease in CD4+ T-cell counts, and high TNF-α and IL-10 levels." (PMID 31024549, 2019). "Sexually transmitted infections, such as syphilis, may also influence the CD4 cell count." (PMID 25768005, 2015). "Also, all STI patients are asked to return for a follow-up visit to receive their syphilis test result, so this could have provided patients with a ready-made opportunity to return to receive their CD4 test result and for timely referral for ART initiation." (PMID 25134822, 2014). "Interestingly, we observed an accumulation of CD4+ T cells in the CSF of both asymptomatic and symptomatic neurosyphilis patients, which were consistent with several previous reports showing that CD4+ T cells were the primary responders to T. pallidum in syphilis lesions." (PMID 24244772, 2013). "In contrast, 37 patients with syphilis coinfection had a mean HIV RNA viral load of 346,788 copies/mL and a mean CD4+ T-cell count of 538.4 cells/μL." (PMID 39941295, 2025). "We present the case of a 65-year-old man who has sex with men and has prior history of treated syphilis and HIV (CD4 >600 cells/mm3; viral load undetectable)." (PMID 38292581, 2024). "Upon further investigation, syphilis and HIV serology were reactive (VDRL 1: 128, TPHA 1: 40960, CD4+ 461 cells/μl)." (PMID 38223877, 2023). "Most infectious disease specialists consider syphilis stage, VDRL titers, and CD4+ cell counts as important parameters when deciding which patients need a lumbar puncture for the investigation of neurosyphilis." (PMID 36043668, 2023). "Most infectious disease specialists still consider syphilis stage, VDRL titers and CD4+ cell counts as important parameters when deciding which patients need lumbar puncture for investigating neurosyphilis." (PMID 36043668, 2023). "The study involved 86 HIV/syphilis co-infected patients and 86 HIV mono-infected patients matched based on age, baseline CD4 + T cell counts, and viral load." (PMID 38288435, 2023). "During incident syphilis, plasma HIV-1 RNA increases and CD4 + T-cell level declines in untreated PWH." (PMID 36587188, 2022). "Among virally-suppressed PWH, total lymphocyte, CD4+, and CD8+ T-celllevels declined duringincident syphilis but rebounded post-treatment." (PMID 36587188, 2022). "The levels of CD4 + and CD8 + T-cells and total lymphocyte count before, during and after syphilis from a group of PWH with pre-existing plasma viral suppression were compared." (PMID 36587188, 2022). "Their plasma HIV-1 RNA, CD4 + and CD8 + T-cell, and total lymphocyte levels before syphilis, during syphilis, and after successful treatment were compared." (PMID 36587188, 2022). "Syphilis can exacerbate HIV infection and inflammation in the central nervous system, increasing HIV viral load and decreasing CD4 + T lymphocyte count." (PMID 36203756, 2022). "Total lymphocyte, CD4+ and CD8+ T-cell levels decreased duringincident syphilis (p<0.01), and rebounded post-treatment (p<0.01)." (PMID 36587188, 2022). "The indications were syphilis treatment failure (3/7), RPR titer ≥ 1:32 (2/7) and peripheral CD4 cell count ≤ 350 cells/mm3 (2/7 cases)." (PMID 35819944, 2022). "Incident syphilis leads to changes in plasma HIV-1 RNA and CD4 + T-cell level in people with HIV (PWH) with viraemia." (PMID 36587188, 2022). "In univariate analysis, we found possible HIV transmission route, ART status, CD4 cell count, serum TRUST titer, previous untreated with syphilis, and were related to the occurrence of neurosyphilis." (PMID 34678871, 2021). "Recent studies in resource-constrained settings have shown that POC syphilis testing and POC CD4+ cell counting are very cost-effective." (PMID 26308345, 2015).
syphilis (continued). "The syphilis, HBV and HCV infection rates, as well as CD4+ T cell counts and viral loads were compared among three APOBEC3B genotype groups (I/I, D/I, and D/D)." (PMID 24667791, 2014). "Syphilis POC test sensitivity and specificity (compared to reference Treponemal immunoassay), overall and by HIV status and CD4 cell count." (PMID 24618681, 2014). "By univariate logistic regression analysis, multiple factors were associated with serological failure, including race (black), syphilis history, RPR titers ≤ 1:16, and a CD4 T-cell count <350 cells/ml." (PMID 24369955, 2013). "There was a positive correlation between the percentage of circulating CD4+ CD25high Tregs and serum TGF-β levels in these syphilis patients (r = 0.20, P<0.05)." (PMID 24244772, 2013). "Absolute number of leukocytes, percentage and numbers of CD4+ T cells, Tregs, and TGF-β levels in CSF from different types of syphilis patients." (PMID 24244772, 2013). "Significant increases in suppressive effect of CD4+ CD25+ Tregs were also observed at ratios of 1∶2 and 1∶4 in secondary and serofast syphilis patients compared with healthy donors." (PMID 24244772, 2013). "Syphilis (active, latent or treated) was positively related to age, HCV infection, and, unexpectedly, lower HIV plasma viral load and higher CD4 count." (PMID 21612634, 2011). "AncillarDiagnostic examinations found the following results: 106 copies/mL HIV viral load; 7/μL CD4 cell; CRF01_AE HIV sub-type; normal liver function; "++" urine WBC; negative results for cytomegalovirus (CMV), herpes, HBV, HCV, and syphilis." (PMID 20230617, 2010). "Clinical care of HIV positive MSM, such as CD4 T cell count or HIV viral load, can conveniently include syphilis testing." (PMID 20429881, 2010). "Specifically, the mean HIV RNA viral load in 163 people living with HIV without syphilis was 874,058 copies/mL, with a mean CD4+ T-cell count of 534.6 cells/μL." (PMID 39941295, 2025). "The study found that the mean CD4+ T-cell count in syphilis-coinfected patients was lower than in those without syphilis (258 vs. 276 cells/μL), with a similar difference observed in the CD4/CD8 ratio." (PMID 39941295, 2025). "The χ2 test showed that all factors, except for ethnicity and CD4 count differed significantly between participants with and without syphilis." (PMID 38962784, 2024). "Moreover, an augmentation in mature CD4+T cells and CD8+T cells was observed in early syphilis, aligning with analogous findings in TBNK results." (PMID 38694502, 2024). "The findings are consistent with existing studies of participants with inconsistent treatment status, suggesting that syphilis-related CD4 + T-cell depletion takes place regardless of HIV-1 suppression status." (PMID 36587188, 2022). "In addition to CD4 + T-cell depletion, previous studies also reported a transient increment of plasma HIV-1 RNA during incident syphilis." (PMID 36587188, 2022). "The median CD4 + T-cell levels (cells/mm3) decreased from 559 (IQR 405–699) before syphilis at T1 to 519 (IQR 390–687) at the time of syphilis diagnosis at T2 (p < 0.001) and rebounded to 562 (IQR 430–725) after successful syphilis treatment at T3 (p < 0.001)." (PMID 36587188, 2022). "In one report, CD4 + T-cell depletion was detected during incident syphilis regardless of HIV status." (PMID 36587188, 2022). "Among the 232 HIV-infected MSM analyzed, CD4+ cell count increased to ≥350 cells/mm3 in 84.8% (78/181) and 73.6% (103/181) of the subjects with or without syphilis testing, respectively." (PMID 34307399, 2021). "However, it was known that infection with syphilis increases the viral load among HIV infected individuals and also decreases the CD4+ T lymphocytes." (PMID 34917677, 2021). "Syphilis had a negative impact on the CD4+T cell counts in HIV-positive patients regardless of treatment." (PMID 35115993, 2021).
syphilis (continued). "Many experts believe that most patients with HIV and syphilis deserve CSF examination regardless of symptoms, especially those with a CD4+ cell count < 350 cells/microL and an RPR > 1:32." (PMID 34832520, 2021). "Multivariate Cox proportional hazards regression analysis indicated that syphilis testing did not directly affect the outcome of CD4+ T cell recovery (P = 0.256)." (PMID 34307399, 2021). "Multivariable Cox regression analysis indicated that syphilis testing per se did not promote the engagement of ART (P = 0.233) or affect the speed of CD4+ T cell count recovery after treatment (P = 0.256)." (PMID 34307399, 2021). "Furthermore, in these patients, a case of untreated syphilis can have direct implications on the course of this disease, leading to increase in plasma HIV viral load and decrease of T CD4+ lymphocytes." (PMID 30362663, 2018). "In conclusion, in HIV-1 infected males who have sex with males, the concomitant presence of HPV-16 and multiple HR genotypes was associated with an increased risk of abnormal cytological findings in addition to a lower CD4+/CD8+ ratio, a positive viral load and with a previous diagnosis of syphilis." (PMID 29088236, 2017). "The characteristics of HIV(+) group were as follows: duration of HIV infection M = 3.7 years, SD = 3.2; CD4 + nadir M = 311 cells/μL, SD = 125; CD4+ current M = 599 cells/μL, SD = 193; duration of cART M = 2.9 years, SD = 2.9; 54 % were diagnosed with STD (syphilis) in the past." (PMID 27356504, 2016). "Uveitis workup revealed positive serology for syphilis and for HIV, with CD4+ cell count of 419/mL." (PMID 26920001, 2016). "Syphilis facilitates HIV transmission due to ulcers that disrupt the epithelial and mucosal barriers as well as inflammation that increase the HIV virus recruitment of CD4 cells, thereby facilitating and increasing the probability of HIV transmission." (PMID 24878586, 2014). "Overall, syphilis increases the risk of HIV-1 transmission and leads to transient increases in HIV-1 RNA plasma levels and decreases in CD4 counts among a subset of patients regardless of the receipt of ART." (PMID 26316953, 2013). "Among the CSF leukocytes, higher percentage of CD4+ T cells were found in patients with asymptomatic (41.8%±2.3%, P<0.01) and parenchymal (46.4%±2.1%, P<0.001) neurosyphilis compared with syphilis patients without neurological involvement (29.7%±2.4%)." (PMID 24244772, 2013). "Treatment of syphilis leads to resolution of the viral load and CD4 cell changes with no apparent long-term impact on HIV-1 progression." (PMID 26316953, 2013). "A multivariate logistic analysis was performed using anal HPV infection as the dependent variable versus a set of covariates: age, HIV plasma viral load, CD4+ count, hepatitis B virus (HBV) serology, hepatitis C virus (HCV) serology, syphilis serology and HHV-8 viral shedding." (PMID 21612634, 2011). "However, in our study, we did not observe a significant impact of syphilis coinfection on HIV RNA levels or CD4+ T-cell counts." (PMID 39941295, 2025). "Moreover, the group with low muscle mass had a lower level of educational attainment (Pgrouped by AWGS criteria = 0.009), a reduced proportion of previous syphilis comorbidity (Pgrouped by AWGS criteria = 0.005) and fewer CD4+ T cells (Pgrouped by quintile = 0.004)." (PMID 39015948, 2024). "Additionally, PLWH and confirmed syphilis had lower median CD4 counts (p-value < 0.01) and fewer were virally suppressed compared to those without syphilis (39.1% vs 48.6%, respectively) (p-value < 0.001)." (PMID 34717564, 2021). "However, other factors, such as the level of CD4 cell count, syphilis stage, and the duration of ART, were not predictors for having asymptomatic neurosyphilis." (PMID 26559304, 2015). "Similarly, the relation between increasing CD4 cell count and lower incidence of syphilis diagnosis was sufficiently precise to rule out chance association only in the combined outcome model." (PMID 26289937, 2015).
syphilis (continued). "According to both univariant and multivariant logistic regressions, we found that CD4 cell count was not a predictor for the asymptomatic neurosyphilis and only the serological TRUST titer was associated with the diagnosis of asymptomatic syphilis." (PMID 26559304, 2015). "Nor sero-prevalence of syphilis was significantly influenced by the level of CD4+ T-cell count." (PMID 25884178, 2015). "Due to preferential accumulation of CD4+ T cells in the CSF of neurosyphilis patients, both asymptomatic and symptomatic neurosyphilis patients have higher numbers of CD4+CD25high Tregs than syphilis patients without neurological involvement." (PMID 24244772, 2013). "Syphilis has been associated with an increase in HIV RNA and a temporary decline in CD4 T cell counts in people living with HIV who are not receiving antiretroviral treatment (ART), and may be associated with a transient HIV RNA rebound in those who are receiving ART." (PMID 32264923, 2020). "Thus, for HIV/syphilis co-infected patients with or without neurological symptoms, CD4 <350 per μL, serological TRUST titer ≥1:16, and neurological symptoms such as hearing loss, vision deficiency, and headache were predictors for performing CSF test for the diagnosis of neurosyphilis." (PMID 26559304, 2015). "Patient 1 was not screened for HIV at the time of secondary syphilis diagnosis and tested positive for HIV-1 1 month later (baseline HIV-1 RNA 12 392 copies/mL, CD4 443 cells/mm3)." (PMID 38464490, 2024). "We did not identify any significant correlations between incident syphilis cases and HIV-related characteristics, including the duration of HIV infection, the duration of ART, CD4+ T-cell count, and HIV viral load > 50 c/mL." (PMID 39065024, 2024). "Healthcare providers must maintain a high index of suspicion for syphilis in HIV-positive patients with visual symptoms, irrespective of their cluster of differentiation 4 (CD4) count or viral load." (PMID 39268262, 2024). "Potential determinants of the changes in CD4+, CD8 + T-cell levels, and total lymphocyte level from T1 to T2, including age, nadir CD4 + T-cell level, CD4/CD8 ratio at T1, VDRL titre, and syphilis reinfection, were compared using non-parametric tests." (PMID 36587188, 2022). "Curiously, baseline RPR titres ≤ 1:16, CD4 counts < 350 cells/μL, untreated HIV infection and a previous syphilis history are considered predictors for persistent non-treponemal titres." (PMID 36556115, 2022). "Our findings argue that the debate over LP is not yet resolved for patients with syphilis who have high serum RPR titers, or in PLWH, who have low CD4+T cells." (PMID 34255767, 2021). "Consistent with the findings from previous studies, our study illustrated that the baseline CD4+ T cell count and early HIV-1 diagnosis were the major factors in predicting post-ART recovery of CD4+ cells, but not syphilis screening." (PMID 34307399, 2021). "Participants had a new syphilis diagnosis, serum RPR titer ≥ 1:32 or peripheral blood CD4+ T cells ≤ 350/ul (in persons living with HIV) and did not endorse neurological symptoms." (PMID 34255767, 2021). "Markers of immune function such as CD4 count and HIV viral load also do not appear to affect serological outcomes among HIV-infected persons with syphilis." (PMID 26511465, 2015). "For other treatable, nonchronic STIs (i.e., syphilis, gonorrhea, and chlamydia), their impact on HIV-1 RNA levels and CD4 cell counts are typically transient and resolve with antimicrobial therapy." (PMID 26316953, 2013). "A diagnostic examination found the following results: 106 copies/mL HIV viral load; 35/μL CD4 cell count; CRF01_AE HIV sub-type; positive results for herpes as well as with Kaposi's sarcoma; negative results for HBV, HCV, and syphilis." (PMID 20230617, 2010).